ALK (ALK receptor tyrosine kinase)
Diseases named in the same sentence as ALK in open-access papers (continued):
Sharing a sentence is not in itself a finding about the gene and the disease.
lung cancer (continued). "Lorlatinib was also reported to cause complete remission of intrathecal metastasis in a heavily pre-treated ALK-positive lung cancer patient, who experienced progression first after chemotherapy plus crizotinib, and second during alectinib treatment." (PMID 29455675, 2018). "All 73 patients were diagnosed with unresectable advanced ALK-positive lung cancer and were treated in our hospital." (PMID 29298713, 2018). "Upon discovery of aberrant ALK activity in lung cancer, the pharmaceutical industry was quick to develop effective targeted therapies that proved to be superior to chemotherapeutic regimens." (PMID 29455675, 2018). "Of note, a DNA-based ALK vaccination also showed a strong ALK-specific CTL immune response that inhibited primary tumor growth in grafted and primary mouse models of ALK-positive lung cancer." (PMID 29642597, 2018). "We examined ciliation in the EML4-ALK-fusion-positive lung cancer cell line NCI-H2228 (which is highly sensitive to the ALK inhibitor NVP-TAE684) and a drug-resistant derivative generated through chronic NVP-TAE684 exposure." (PMID 29874589, 2018). "Molecular testing is carried out systematically on all patients with lung cancer in France and EGFR mutations and ALK rearrangements are observed in around 16% of patients." (PMID 30348130, 2018). "Anaplastic lymphoma kinase tyrosine kinase inhibitors (ALK-TKIs) induce a dramatic response in non–small cell lung cancer (NSCLC) patients with the ALK fusion gene." (PMID 29930762, 2018). "This is not surprising since these patients have acquired mutations during the course of the disease (EGFR T790 M) and the fact that this dataset includes fusions (ROS1, ALK in lung cancer, ABL1 in leukemia)." (PMID 29544535, 2018). "A recent study indicates that there are at least three mechanisms by which EGFR activation can promote resistance to therapy targeting oncogenic kinase fusions in lung cancer, including those directed at ALK." (PMID 29455675, 2018). "Non-small cell lung cancer (NSCLC) with rearrangement of the anaplastic lymphoma kinase (ALK) gene is a distinct subtype of lung cancer." (PMID 29524063, 2018). "Rearrangements of the anaplastic lymphoma kinase (ALK) gene have been detected in 3% to 7% of non–small cell lung cancers (NSCLCs)." (PMID 29796191, 2018). "Although they represent a small proportion of NSCLC cases, the absolute number of ALK-positive NSCLC patients is greater than that of ALK-positive ALCL due to the greater worldwide incidence of lung cancer." (PMID 29455675, 2018). "Several small molecule targeted agents have been developed against the EGFR and ALK tyrosine kinases, which have increased hope for patients with brain metastases of lung cancer." (PMID 29435193, 2018). "ALK rearrangements included EML4-ALK fusions have been identified in 3–7% of patients with NSCLC (herein referred to as “ALK-positive” lung cancer)." (PMID 30453899, 2018). "It is approved for treatment of ALK- or ROS1-rearranged lung cancer and undergoing clinical trials in patients with other advanced solid tumors." (PMID 29755689, 2018). "ALK rearrangements have been found in multiple malignancies, including lung cancer, neuroblastoma, rhabdomyosarcoma, renal cell carcinoma, and inflammatory breast cancer." (PMID 29455670, 2018). "It seems evident from the recent success of ceritinib and the fast-track FDA approval of alectinib that genomic profiling of NSCLC tumors is necessary to personalize the treatment of ALK-positive lung cancer patients." (PMID 29455642, 2018). "ALK fusion should be part of lung cancer routine diagnosis for all stage IV patients as it is easy to detect using immunohistochemistry (IHC) as a screening tool." (PMID 29890761, 2018). "Although some Chinese patients bought crizotinib from overseas before the approval, many more Chinese patients with advanced ALK-positive lung cancer received crizotinib treatment after its approval." (PMID 29298713, 2018).
lung cancer (continued). "More impressively, the OS for patients with metastatic ALK-positive lung cancer in this cohort exceeded 4 years from the time of metastasis diagnosis." (PMID 29455675, 2018). "Sensitivities of 0.005–0.1% for EGFR-T790M (own unreported data,), 0,1% and 0,5% for ALK-C1156Y and ALK-G1269A in lung cancer and 0.025% for KRAS in CRC are reached." (PMID 29568401, 2018). "As ALK-positive lung cancer patients benefit from tyrosine kinase inhibitor therapy in the first-line setting, ALK must be tested at the time of diagnosis." (PMID 28970558, 2017). "Lung cancer patients with anaplastic lymphoma kinase (ALK) rearrangements are candidates for targeted therapeutics." (PMID 28032602, 2017). "The epidermal growth factor receptor (EGFR) and anaplastic lymphoma kinase (ALK) genes are the most important drivers in lung cancer." (PMID 29167003, 2017). "In this study, we performed a direct comparison of formalin-fixed paraffin-embedded (FFPE) lung cancer specimens using all three ALK detection methods." (PMID 28763012, 2017). "Katayama, R. (2017) Therapeutic strategies and mechanisms of drug resistance in anaplastic lymphoma kinase (ALK)‐rearranged lung cancer." (PMID 29055036, 2017). "Immuno-histochemical examination of the tumor demonstrated ALK overexpression and the presence of an ALK rearrangement observed in lung cancers." (PMID 28409069, 2017). "In the present study, we intended to validate a NanoString nCounter ALK-fusion panel in routine biopsies of FFPE lung cancer patients." (PMID 28549458, 2017). "In this study, we investigated the ability of a RT-PCR assay using a ΔCt ≤ 8 to detect ALK expression in lung cancer FFPE samples from an enriched cohort of 95 patients and compared the results to FISH and IHC." (PMID 28763012, 2017). "In summary, we have shown that RaFISH can be used as a clinical tool for prompt determination of ALK status in lung cancer samples." (PMID 29118432, 2017). "In this review, we present the genomic landscape of ALK fusions in the context of co-occurring mutations with other cancer-related genes, pointing to the central role of genetic epistasis (gene-gene interactions) in ALK-driven advanced-stage lung cancer." (PMID 29189709, 2017). "We concluded that IGF-1R is an independent druggable target in ALK-positive lung cancer and support the trial of combination treatment." (PMID 29066738, 2017). "While ALK TKIs have had a major impact on lung cancer care, novel therapeutic approaches for ALK-positive cancers are necessary to provide safe and durable responses for patients." (PMID 29190913, 2017). "Anaplastic lymphoma kinase (ALK) gene rearrangements have been identified in lung cancer at 3–7% frequency, thus representing an important subset of genetic lesions that drive oncogenesis in this disease." (PMID 29189709, 2017). "Translocation were reported in two samples, one was in ALK in a lung cancer sample and the other in RET in a thyroid cancer case." (PMID 28371134, 2017). "Experimental evidence showed that lung cancers with ALK fusion harbor an immune-suppressive TME and a T-cell exhausted state." (PMID 29189709, 2017). "In recent years molecular subtyping has become an important tool for accurate diagnosis of many cancers; for example, the detection of ALK rearrangements in lymphoma and lung cancer helps clinicians provide more precise diagnosis and treatment." (PMID 27974674, 2017). "ALK-rearranged lung cancers exhibit specific pathologic and clinical features and are responsive to anti-ALK therapies." (PMID 28549458, 2017). "Patients with lung cancers harboring an activating anaplastic lymphoma kinase (ALK) rearrangement respond favorably to ALK inhibitor therapy." (PMID 28763012, 2017). "Epidermal growth factor receptor (EGFR) and anaplastic lymphoma kinase (ALK) are the two common biological targets for lung cancer drug development." (PMID 28615068, 2017).
lung cancer (continued). "For example, when lung cancers with the EML4-ALK fusion were treated with ALK inhibitor alone, either adaptive signaling or acquired mutations resulted in reactivation of the MAPK pathway." (PMID 28431544, 2017). "We confirmed that combination ALK and IGF-1R inhibitor treatment is synergistically cytotoxic to ALK-positive lung cancer cells and that this remains the case for at least 12 days after initial exposure to crizotinib." (PMID 29066738, 2017). "More recently, the PROFILE 1014 study in ALK-positive lung cancer patients demonstrated that crizotinib can increase PFS and ORR in comparison with first-line platinum-based agents." (PMID 28427213, 2017). "A total of 73 participants, including 41 patients with ALK-positive lung cancer and 32 patients with ALK-negative lung cancer, were enrolled in the validation phase of the present study." (PMID 28514730, 2017). "While patients with EGFR- and ALK-mutant lung cancer do often respond to EGFR and ALK inhibitors, these responses are temporary, as acquired resistance inevitably develops." (PMID 28145866, 2017). "Circulating microRNAs are potential diagnostic and predictive biomarkers, but have not been investigated for patients with anaplastic lymphoma kinase (ALK)-positive lung cancer." (PMID 28514730, 2017). "Aberrant ALK fusions were recently identified in a subset of lung cancer patients, resulting in the constitutive activation of MEK/ERK and PI3K pathways, with consequent up-regulation of cell survival and proliferation mechanisms." (PMID 28549458, 2017). "ALK is another important target in lung cancer since it leads to treatment of patients who are positive for a rearrangement in ALK identified with tumor tissue." (PMID 29125548, 2017). "We have found that KEAP1 loss modulates sensitivity to inhibition of EGFR, ALK, BRAF, or MEK in lung cancer cell lines with EGFR, ALK, BRAF, KRAS, or NRAS mutations." (PMID 28145866, 2017). "Crizotinib obtained accelerated approval in 2011 for treating metastatic non–small-cell lung cancer (NSCLC) based on two single-arm studies restricted to patients positive for anaplastic lymphoma kinase (ALK)." (PMID 28761069, 2017). "The developments of platinum-based chemotherapy and targeted therapies for EGFR-sensitive and ALK-positive patients have been regarded as milestones for lung cancer treatment." (PMID 29137407, 2017). "Here we established anaplastic lymphoma kinase (ALK)‐positive drug‐resistant lung cancer cell lines, which are resistant to ceritinib (LDK378)." (PMID 28396832, 2017). "HSPC1 inhibitors show moderate success as monotherapy in lung cancer with ALK re-arrangement and in combination with transtuzumab in HER2+ breast cancer." (PMID 28255900, 2017). "Initially found in non-small cell lung cancer (NSCLC), EML4-ALK fusion has been regarded as an important event in the development of lung cancer and an indication for the application of crizotinib (an ALK inhibitor)." (PMID 28535796, 2017). "In the present study, we sought to implement the NanoString panel of ALK fusion detection for lung cancer patients and to optimize its applicability in biopsies using up to 100 ng of RNA." (PMID 28549458, 2017). "Several orally available small molecule ALK inhibitors have been developed and successfully applied in patients with other ALK mutant tumour entities, so-called ALKoma’s, most notably a subset of lung cancers." (PMID 29290991, 2017). "At present, molecular-targeted therapies of lung cancer are confined to those targeting EGFR and ALK mutations." (PMID 28415711, 2017). "The use of ALK-TKIs significantly increases the risk of developing high-grade ILD and QTc prolongation in lung cancer patients." (PMID 28915678, 2017). "Recently, epidermal growth factor receptor (EGFR) and anaplastic lymphoma kinase (ALK) have been determined to be the most effective molecules for targeted therapy in lung cancer." (PMID 28272300, 2017).
lung cancer (continued). "Taken together, ALK rearranged lung cancer appears to exhibit an immune-suppressive or anergic tumor microenvironment." (PMID 29189709, 2017). "Since the discovery of the EML4-ALK fusion oncogene in lung cancer in 2007, targeted therapies aiming to inhibit the constitutively activate ALK kinase domain have been the main focus for cancer therapy." (PMID 29189709, 2017). "Alectinib shows remarkable efficacy against anaplastic lymphoma kinase (ALK)-positive nonsmall cell lung cancer (NSCLC), with minimal adverse effects." (PMID 28588841, 2017). "Its pathological expression in lung cancer and most other malignancies is due to chromosomal translocations that lead to the formation of an ALK-derived oncogenic fusion proteins, which are overexpressed and constitutively activated in cancer cells." (PMID 29189709, 2017). "Another example of drug resistance in lung cancer is anaplastic lymphoma kinase (ALK) target treatment." (PMID 27757846, 2017). "PD-L1 expression is increased in ALK+ lung cancer cells through downstream pathway signaling, in particular ERK and AKT activation but not JAK/STAT3/5 signaling." (PMID 29189709, 2017). "These inhibitors are studied mostly in the context of more prevalent ALK+ cancers for which clinical trials are easier to populate, particularly ALK+ lung carcinoma." (PMID 29035291, 2017). "While several fusion genes involving ALK produced by chromosomal rearrangements have been found in a subset of lymphomas and lung carcinomas." (PMID 28837676, 2017). "Like ALK rearrangements in other tumors, ALK rearrangements in lung cancer frequently occur in younger patients." (PMID 26992209, 2016). "This is particularly important in lung cancer: repeat biopsy is rarely performed, even though various studies have shown discrepancies in EGFR, ALK and KRAS mutational status." (PMID 26968843, 2016). "Although the adnexal location is an uncommon metastasis site from lung cancer, oncologists should be aware of the possibility of such metastasis for female patients with ALK rearrangement NSCLC." (PMID 27472693, 2016). "The phase 3 studies (JapicCTI-132316, NCT02075840) comparing alectinib with crizotinib in the patients with chemo-naive, advanced ALK-rearranged lung cancer are ongoing." (PMID 26987388, 2016). "The identification of ALK translocations in NSCLC has opened the door to the use of targeted therapies for the treatment of these lung cancers." (PMID 27206799, 2016). "A variety of agents that target EGFR (epidermal growth factor receptor), ALK (anaplastic lymphoma kinase), or ROS1 (c-ros oncogene 1) have improved the outcome of lung cancer patients bearing specific driver mutations." (PMID 27835880, 2016). "In consideration of its function played in other tumor types such as lung cancer and neuroblastoma, the possible therapeutic role of ALK in RMS needs to be further investigated in in vitro models and, ultimately, in in vivo pharmacological studies." (PMID 27385213, 2016). "In this lung cancer histology, mutations in KRAS and EGFR and ALK translocations account for the 15–25%, 10–35%, and 2–5% of cases, respectively, the two latter being TKRs." (PMID 27528792, 2016). "HRs from vital‐sign data for patients with anaplastic lymphoma kinase (ALK)‐positive nonsmall cell lung cancer enrolled in PROFILE 1005 and the crizotinib arm of PROFILE 1007 were analyzed." (PMID 26823131, 2016). "In lung cancer, the fusion of ALK with EML4 leads to constitutive activation of ALK, directly affecting downstream signaling and increasing cell proliferation and survival." (PMID 27495736, 2016). "Mutations in the gene encoding epithelial growth factor receptor (EGFR), rearrangements of the gene encoding anaplastic lymphoma kinase (ALK), and other oncogenic drivers, such as BRAF, are the most common genomic changes in lung cancer." (PMID 27746286, 2016). "Crizotinib, a novel ALK tyrosine kinase inhibitor, has already shown an impressive single-agent activity in ALK positive lung cancer." (PMID 27472693, 2016).
lung cancer (continued). "After that, several research groups have reported the presence of these fusions in patients who integrate a new molecular subset of lung cancer with similar characteristics to ALK-positive and ROS1-positive patients." (PMID 27528792, 2016). "Anaplastic lymphoma kinase (ALK)-positive non-small cell lung cancer (NSCLC) is an important subtype of lung cancer.The standard modality of ALK-positive NSCLC with brain metastases remains uncertain." (PMID 27561801, 2016). "Soon after the discovery of ALK translocations in lung cancer, patients harboring this fusion gene demonstrated impressive response rates in clinical trials when treated with the ALK inhibitor crizotinib." (PMID 27495736, 2016). "The guideline suggests that lung cancer tissues are tested by PCR for EGFR mutations and by FISH for ALK mutations." (PMID 27448564, 2016). "Although it is still a relatively new field (ALK mutations in NSCLC were discovered in 2007 and crizotinib was granted accelerated approval in 2011), ALK inhibitors can be given to lung cancer patients on a biomarker-based approach." (PMID 27350784, 2016). "Undoubtedly, tyrosine kinase inhibitors (TKI) for EGFR and ALK are currently the standard of care for EGFR-mutant and ALK-rearranged lung cancer patients, respectively." (PMID 26992220, 2016). "The availability of these targeted therapies has prompted the development of diagnostic assays and algorithms that can accurately identify ALK-positive lung cancers patients." (PMID 27206799, 2016). "Given that ALK-positive lung cancer involves the lymph nodes, there are several clinical treatment strategies (e.g., lymph node radiation after resection of the ALK-positive lung cancer)." (PMID 27518729, 2016). "It was approved by the US Food and Drug Administration (FDA) for treating advanced stage ALK-positive lung cancer." (PMID 27217997, 2016). "Crizotinib, as a well known anti-ALK drug (PF02341066) was used for the treatment of some tumors, such as a non–small-cell lung cancer with ALK rearrangements." (PMID 26735175, 2016). "In spite of the considerable published data on the prevalence of EGFR mutations in lung cancer throughout the world, only a few papers present data on EGFR, KRAS and ALK mutations in countries from Central Europe." (PMID 27655296, 2016). "The standard molecular testing for lung cancer is to check for mutations of two molecules: epidermal growth factor receptor (EGFR) and rearrangement of anaplastic lymphoma kinase (ALK)." (PMID 26944944, 2016). "Epidermal growth factor receptor-tyrosine kinase inhibitors (EGFR-TKIs) and anaplastic lymphoma kinase (ALK) inhibitors have dramatically changed the strategy of medical treatment of lung cancer." (PMID 27070423, 2016). "Annual lung cancer-specific ALK testing volume ranged from 150 to 1500 among laboratories in the U.S., and from 200 to 3600 among laboratories in Europe." (PMID 26838801, 2016). "For instance, EGFR and ALK have been identified as key biomarkers in lung cancer, and molecular tests for EGFR and ALK have become common in lung cancer treatment." (PMID 27589834, 2016). "The ALK-translocated patients were identified as a category with different features from large lung cancer population." (PMID 27433281, 2016). "Nonetheless, the converging trend of both studies’ findings is indicative of the utility and potential of CTCs as an alternate target of ALK testing in lung cancer and informs the development of CTC-based technology." (PMID 26993609, 2016). "We further explored the potential use of CTCs in lung cancer, as a surrogate for molecular testing of the primary tumor for ALK gene rearrangement." (PMID 26993609, 2016). "Regarding lung cancer, the presence and potential prognostic role of the different ALK gene aberrations (translocation and gene copy number gains) have been widely investigated with debatable results (as more extensively revised in the discussion paragraph)." (PMID 27561692, 2016).